RNY4P19 (RNY4 pseudogene 19)
Gene: Miscellaneous RNA gene on chromosome 2 (230,058,229 to 230,058,324, reverse strand). Ensembl gene ENSG00000199400.
Homologues: Orthologues: chimpanzee Y_RNA (99% identical), macaque Y_RNA (96% identical). Paralogues in human: RNY4 (91% identical), RNY4P37 (91% identical), RNY4P6 (90% identical), RNY4P7 (89% identical), RNY4P25 (88% identical), RNY4P36 (88% identical), Y_RNA (88% identical), RNY4P10 (86% identical), RNY4P13 (86% identical), RNY4P14 (86% identical), RNY4P3 (86% identical), RNY4P9 (86% identical), and 88 more.